CCL2 (C-C motif chemokine ligand 2)
Diseases named in the same sentence as CCL2 in open-access papers (continued):
Sharing a sentence is not in itself a finding about the gene and the disease.
depression (continued). "It is a possible mediator of the pathogenesis of depression since previous studies have demonstrated that serum CCL2 is elevated in major depressive disorder and reduced after antidepressant treatment." (PMID 35504954, 2022). "Previous studies with major depressive disorder, schizophrenia, and generalized anxiety disorder showed that higher levels of IL-1β, IL-2, IL-6, and CCL2 were related to the severity of psychiatric symptoms." (PMID 35504954, 2022). "CCL5, CCL2, and CCL11 were significantly associated with anxiety and depression in a study on the uterine–chemokine–brain axis." (PMID 36614020, 2022). "We note that serum levels of CCL2/MCP-1 were reported to be lower in patients with major depressive disorder than in healthy controls." (PMID 34979499, 2022). "TARC/CCL17 and Eotaxin/CCL11 showed significant associations with high scores for depression (p < 0.04) whereas, MCP-1/CCL2 and MIP-1α/CCL3 were significantly associated with high scores for anxiety (p < 0.05) in the ANX + DEP group." (PMID 34863117, 2021). "Further support for the important role of CCL2 in the pathogenesis of depression came from the observation that this chemokine is involved in the release of certain neurotransmitters in the brain." (PMID 34031863, 2021). "Using a multivariate linear model, high serum levels of MIP-1β/CCL4 and Eotaxin/CCL11 remained associated with depression (p < 0.01), while, IL-8/CXCL8, MIP-1β/CCL4, MCP-1/CCL2, and MIP-1α/CCL3 were associated with anxiety (p < 0.05) in the symptomatic groups." (PMID 34863117, 2021). "A number of cross-sectional studies have found links between depression and cytokines such as CCL2, IL8 and CCL1123." (PMID 31974503, 2020). "Clinical studies also show that pro-inflammatory cytokines, e.g. TNF-α, IL-1β, IL-6, CCL-2, and IL-18, increase in patients with depression or anxiety." (PMID 32010477, 2020). "A recent meta-analysis reported higher CCL2 levels in patients with major depression compared to healthy controls." (PMID 29520075, 2018). "Other studies have also shown that CCL2 levels were significantly higher in patients with major depression and in female patients with stress-related mental disorders." (PMID 30504920, 2018). "These include CXCL1 (Gro-α), CCL2, CCL7 (MCP-1, MCP-3), and CCL5 (RANTES), which have also been implicated in various behavioral impairments including anxiety, depression, and LM." (PMID 29358844, 2017). "We confirmed that the M1 markers (IL-1β, IL-6, TNFα, iNOS, and CCL2) were induced and that the M2 molecules (Ym1, Arg1, IL-4, IL-10, and TGFβ) were impaired in depression." (PMID 27716270, 2016). "CCL2/MCP-1 levels correlated with symptoms of depression, as assessed by the Hospital Anxiety and Depression Scale, and UPDRS motor score." (PMID 25386381, 2014). "The considerable role of CCL2 on the CNS has been noticed to be involved in various neurobiological processes, along with reduced synaptic transmission/plasticity and neuronal excitability, and has had functional consequences on depression." (PMID 40237232, 2025). "Several depression-related cytokines including CCL2, IL-6, and IL-10 were significantly increased." (PMID 39409106, 2024). "Interestingly, a positive Spearman correlation was maintained at the mRNA level in PBMCs of depression patients, between CCL2, IL-6 and TNF-α." (PMID 37575572, 2023). "NPI-Q question 4 (depression) severity was higher in CCL2 (p-value = 0.024)." (PMID 35504954, 2022). "Moreover, some more in-depth studies revealed an increase in the concentration of chemokine such as C-C motif chemokine ligand 2 (CCL-2) among patients with depression." (PMID 35757204, 2022). "However, on each question of the NPI-Q, the severity of depression/dysphonia reflected in question 4 was higher in Q4 of CCL2 (Q1 0 (0–1.0) and Q4 1.0 (0–2.3); p-value = 0.024)." (PMID 35504954, 2022).
depression (continued). "The aim of this study was to test the relationship between depression and plasma concentrations of CCL2, CCL11, CX3CL1 and CXCL12 in mildly and moderately depressed primary-care patients, as well as the potential influence of an effective iCBT intervention on those molecules." (PMID 31974503, 2020). "Additionally, the Q4 of CCL2 revealed a higher severity of depression on the NPI-Q." (PMID 35504954, 2022). "Thus, it is possible that lower CCL2 in depression identifies a more severe, TRD group." (PMID 32699209, 2020). "TNFα, IL-10, and MCP-1 (CCL2), biomarkers of inflammation, are also increased in people with depression." (PMID 39337564, 2024). "Polymorphisms in genes such as IL-1β, IL-6, IL-10, TNF, MCP1/CCL2, CRP, and phospholipase A2 are among the most consistently observed findings in major depressive disorder." (PMID 39723161, 2024). "Studies report that the plasma levels of proinflammatory cytokines such as interleukin-1β (IL-1β), IL-6, IL-12, CC chemokine Ligand (CCL-2), Tumor Necrosis Factor (TNF)-α, prostaglandin E2 are increased in patients suffering from depression." (PMID 38473935, 2024). "Increased levels of proinflammatory mediators and markers, such as CCL2, CRP, and IL-6, were found in patients with severe depression." (PMID 38931342, 2024). "The results show a pro-inflammatory profile in plasma of depression patients, with increased TNF-α and CCL2, as well as significant correlations between the levels of different pro-and anti-inflammatory mediators." (PMID 37575572, 2023). "Depression patients were found to have a pro-inflammatory profile in plasma, with significantly higher levels of TNF-α and CCL2 compared with controls." (PMID 37575572, 2023). "Globally, we show that depression patients have increased systemic inflammation, reflected on increased plasma levels of TNF-α and CCL2, increased TNF-α mRNA levels in PBMCs, and dysregulated expression of key and inflammation-related miRNAs in PBMCs." (PMID 37575572, 2023). "Depression patients were found to have significantly higher levels of TNF-α and CCL2 in the plasma, and increased expression levels of TNF-α together with decreased IL-6, in PBMCs." (PMID 37575572, 2023). "Among them, chemokine CCL2 and its main receptor CCR2 have become candidate mediators of abnormal brain-immune system dialogue in depression." (PMID 34031863, 2021). "Positive correlations were observed between MIP-1α/CCL3, MIP-1β/CCL4, MCP-1/CCL2, MIP-3α/CCL20, RANTES/CCL5, Eotaxin/CCL11, and I-TAC/CXCL11 with high scores for anxiety (HARS) (p < 0.05) and for depression (HDRS) (p < 0.004)." (PMID 34863117, 2021). "PD patients have elevated levels of CRP, CCL-2, IL-6, and of TNF-alpha, correlating partially with fatigue, depression and anxiety, and with cognitive deficits." (PMID 32072462, 2020). "CCL2 and CXCL12 are chemokines involved in the RSD model of depression, characterised by increased inflammation and glucocorticoid resistance." (PMID 32699209, 2020). "A number of studies show that plasma CCL2 levels differ in SZ, ASD, BD and major depression compared to controls." (PMID 25905630, 2015). "This highlights the importance of the CCL2/CCR2 signaling and suggests a possible link with depressive disorders." (PMID 25065370, 2014). "Furthermore, STRING analysis underscored the shared roles of specific proteins, including EGFR, IL15, CCL2, and CCL20, in the context of air pollution-induced depression and anxiety, highlighting the involvement of immune-related processes and pathways." (PMID 40611827, 2025). "High levels of CCL2 and CCL13 were observed in patients with depression compared to healthy control, evoking the possibility that immune cell mobilization may be involved in the disease." (PMID 38473935, 2024). "While mostly increased serum CCL2 level has been shown in patients suffering from depression, the lack of therapeutic effect of antidepressants was correlated with a low initial or final serum concentration of this chemokine." (PMID 34031863, 2021).
depression (continued). "Our research suggests that the concurrent upregulation of CCL2 and CCL20 in response to air pollution may have a synergistic effect in promoting neuroinflammation, thereby mediating the relationship between air pollution and depression and anxiety." (PMID 40611827, 2025). "When compared with participants without depression or subsequent cognitive decline, patients with LLD were shown to have elevated concentrations of CCL-2 and CCL-4 and cytokines IL-17a, IL-33, IFN-γ and IL-1ra, as well as IL-33 in most models." (PMID 39922907, 2025). "This meta-analysis indicates that a number of these chemokines (CCL2, CCL3, CCL4, CCL11, CXCL4, CXCL7 and CXCL8) when measured in the blood discriminate between those with and without depression." (PMID 29133955, 2018). "In general, TRD and drug-free patients had similarly increased levels of inflammation-related genes: this applied to both the genes that had been measured before in depression (IL1-beta, IL-6, TNF-alpha and MIF) and those never measured before (A2M, CRP, P2RX7, CCL2 and STAT1)." (PMID 32699209, 2020).
renal fibrosis (123 papers, 2012 to 2026). A final common manifestation of a wide variety of chronic kidney diseases characterized by glomerulosclerosis and tubulointerstitial fibrosis. "CCL2 has recently been introduced as one of main causative factors for the development of renal fibrosis by promoting the accumulation of immune factors in kidney interstitium and releasing profibrotic factors, therefore leading to decreased graft survival." (PMID 34768469, 2021). "Confirming our dose range experiments, X203 reduced AKI-induced loss of kidney mass, limited renal fibrosis, and improved renal function while lowering inflammatory (Tnfα, Il6, Ccl2, Ccl5, Il1β), fibrosis (Col1a1, Col1a2, Col3a1, Fn1, Acta2) and tubular damage (Kim1, Ngal) markers." (PMID 36470928, 2022). "Consistently, angiotensin-converting enzyme 2 (ACE2), which is inversely correlated with CCL2 expression, is strongly associated with CKD and is known to limit renal fibrosis." (PMID 39850880, 2024). "In diabetic nephropathy-induced renal fibrosis, silencing of lncRNA Meg3 inhibited LPS-induced production of CCL-2 and CXCL-2 cytokines, which ameliorated renal fibrosis in mice." (PMID 39113708, 2024). "Proteomic analysis of an in vitro model of renal fibrosis identified CCL2 as a key factor contributing to collagen deposition in the kidney." (PMID 39850880, 2024). "Improved eGFR and reduced renal fibrosis and inflammation by downregulating inflammatory genes like C3, CCL2, and TNFα and modulating angiogenesis, fibrosis, inflammation, and proliferation pathways." (PMID 38929190, 2024). "The therapeutic inhibitors of renal fibrosis were shown to downregulate the expression of CCL2 in renal cells." (PMID 38137543, 2023). "The possible role of CCL2 in renal fibrosis and worsening renal function was also highlighted following a systematic review." (PMID 33670423, 2021). "Many previous reports have suggested that CCL2 expression in the renal tissue of animal models is closely related to the development of renal fibrosis due to CNI toxicity." (PMID 32787951, 2020). "In the early stages of UUO, the pro-inflammatory macrophage (M1) is the predominant macrophage phenotype, directly inducing renal fibrosis by releasing pathogenic mediators such as TNF-α, IL-1β, CCL2 and reactive oxygen species (ROS)." (PMID 28416741, 2017). "Clinical evidence suggests that MCP-1/CCL2 could serve as a biomarker for predicting renal fibrosis and deterioration in function." (PMID 39749340, 2024). "According to the reports, monocyte chemoattractant protein 1 (MCP-1) encoded by CCL2 was a biomarker in kidney diseases, suggesting kidney damage and inflammation, and CCL2 itself increased in macrophages and was related to renal fibrosis in a renal atrophy model." (PMID 36967395, 2023). "The CCL2-dependent recruitment of macrophages to the nerve injury site is most likely initiated by the mechanically activated cationic channel Piezo1, as it was suggested for macrophages involved in renal fibrosis." (PMID 36293246, 2022). "Persistent stimulation will ultimately lead to in situ renal fibrosis and, subsequently, renal damage Thus, urinary CCL2 levels following bariatric surgery may be used as a surrogate marker to the ongoing renal inflammatory process." (PMID 31964990, 2020). "In high-fat diet and STZ-induced DN rats, berberine and Tangshen Formula can not only inhibit the up-regulation of IL-1β, TNF-α, and CCL2 by inactivating the NF-κB signaling pathway, but also attenuate renal fibrosis via the TGF-β/Smad3-mediated signaling pathway." (PMID 32365893, 2020). "Furthermore, enhanced renal fibrosis, mesangial proliferation, podocyte loss, TGF-β, CCL2 expressions, and suppressed Rho levels are observed in renal tissues in STZ-induced DN rats." (PMID 32365893, 2020).
renal fibrosis (continued). "Real‐time PCR analysis found elevated levels of mRNA for markers of renal inflammation (CD68, TNF‐α, CCL2) and renal fibrosis (TGF‐β1, fibronectin, collagens I and IV) in diabetic compared to nondiabetic kidneys, which were not different in male and female mice." (PMID 31535473, 2019). "Reduced expression levels of inflammatory factors such as C-Reactive Protein (CRP) and C-C Motif Chemokine Ligand 2 (CCL2) enhance kidney function, decrease renal fibrosis, and improve inflammation control." (PMID 38362272, 2024). "The result is the increased expression of genes C-C Motif Chemokine Ligand 2 (CCL2) and C-C Motif Chemokine Ligand 5 (CCL5) and further renal fibrosis." (PMID 39125360, 2024). "Among the chemokines, monocyte chemoattractant protein-1 (MCP-1), also known as C-C motif chemokine ligand 2, together with its main receptor C–C chemokine receptor type 2 (CCR2) are important chemokines in renal fibrosis." (PMID 37861543, 2023). "A study reported that BMMSCs can decrease levels of tubular CCL-2, CCL-5, TNF-α, α-SMA, fibronectin (FN), and collagen IV and finally reduce tubular EMT and renal fibrosis in albumin-overloaded mice." (PMID 36268508, 2022). "Also, the levels of damage markers in renal fibrosis, including ED-1 α-SMA, IL-6, IL-1β, TNF-α, TGF-β, NF-κB mRNA, CCL-2, CCL-5, collagen I, FN, collagen IV, and PCNA are decreased." (PMID 36268508, 2022). "In biopsy specimens of patients with IgAN, CCL2, and CCL5, also known as regulated upon activation normal T-cell expressed and secreted (RANTES), as well as CCR5 were up-regulated and could play a role in renal fibrosis." (PMID 33670423, 2021).
hepatocellular carcinoma (118 papers, 2010 to 2026). A malignant tumor that arises from hepatocytes. "HOTAIR, highly expressed and associated with poor prognosis in hepatocellular carcinoma, promoted the secretion of CCL2 in hepatocellular carcinoma cells and increased the proportion of macrophages and MDSCs." (PMID 36831498, 2023). "Tumor-associated macrophage blockade by anti-chemokine (C-C motif) ligand 2 (CCL2) antibody inhibited hepatocellular carcinoma progression, while depletion of all macrophages had a tumor-promoting effect by increasing myeloid-derived suppressor cells (M-MDSCs) and decreasing CD8 T cells." (PMID 36828281, 2023). "Indeed, it has previously been demonstrated in hepatocellular carcinoma that tumor-associated neutrophils recruited macrophages via CCL-2." (PMID 35883641, 2022). "CSF‐1, CCL2, and IL‐15 are found to enhance the clearance of macrophages on hepatocellular carcinoma (HCC) cells." (PMID 41427020, 2025). "In vitro and in vivo experiments have also confirmed that the downregulation of IL-6 or MCP1 (CCL2) in hypoxia inhibits HIF-1α expression in hepatocellular carcinoma." (PMID 40430040, 2025). "This inhibition leads to the reduced expression and secretion of CCL2, consequently suppressing the migration and invasion of hepatocellular carcinoma (HCC) cells." (PMID 39336801, 2024). "Similar observations were found in adipocytes co-cultured with exosomes derived from hepatocellular carcinoma, where the induction of pro-inflammatory cytokines IL-6, IL-8, IL-1β and CCL2 promoted tumor growth and angiogenesis." (PMID 37833751, 2023). "Two chemokines, chemokine ligand 2 (CCL2) and CCL5, play major roles in the accumulation of tumor-associated macrophages (TAMs) and induction of immunosuppression in hepatocellular carcinoma (HCC)." (PMID 36839944, 2023). "In hepatocellular carcinoma, the CCL2/CCR2 axis promotes macrophage infiltration and forms an immunosuppressive microenvironment." (PMID 36018370, 2023). "Hsa-circ-0110102, as a cancer-causing circRNA, inhibits the expression of CCL2 in HCC cells through the sponge effect of miR-580-5p, CCL2 further activates the COX-2/PGE2 pathway in macrophages in a FOXO1-dependent manner, and promotes the progress of hepatocellular carcinoma." (PMID 35806027, 2022). "miR 580 has been shown to inhibit chemokine ligand 2 (CCL2) production in the hepatocellular carcinoma tumor microenvironment." (PMID 36033825, 2022). "Targeting and suppression of tumor‐infiltrating macrophages via CCL2/CCR2 signaling was a therapeutic strategy against hepatocellular carcinoma." (PMID 36039642, 2022). "Previous studies have also demonstrated the translational potential of CCL2/CCR2 in hepatocellular carcinoma, pancreatic cancer and esophageal squamous cell carcinoma." (PMID 34745969, 2021). "Mice carrying a miR-122 knockout displayed upregulated hepatic CCL2 expression leading to hepatitis and hepatocellular carcinoma." (PMID 33540898, 2021). "Treatment with neutralizing CCL2 Ab suppressed chronic liver inflammation, reduced liver damage and both liver carcinoma incidence and tumor burden by downregulating pro-inflammatory pSTAT3, c-MYC, and NF-κB signals." (PMID 33540898, 2021). "Circular RNA hsa_circ_0110102 functions as a molecular sponge to inhibit CCL2 transcription in hepatocellular carcinoma (HCC) cells, which further inhibits macrophage recruitment." (PMID 34386431, 2021). "For example, hepatoma cell lines overexpressing the lncRNA HOTAIR secreted more C-C motif chemokine ligand 2 (CCL2) than control cell lines, which promoted the proliferation of tumor-associated macrophages and myeloid-derived suppressor cells." (PMID 33329695, 2020). "In hepatocellular Carcinoma, FoxQ1 expression promotes macrophage infiltration through the VersicanV1/CCL2 axis." (PMID 32653013, 2020). "Hepatoma cell lines with HOTAIR overexpression secreted higher CCL2 and this promotes TAM and MDSCs proliferation." (PMID 31072041, 2019).